CSDE1 (cold shock domain containing E1)
Description:
RNA-binding protein involved in translationally coupled mRNA turnover. Implicated with other RNA-binding proteins in the cytoplasmic deadenylation/translational and decay interplay of the FOS mRNA mediated by the major coding-region determinant of instability (mCRD) domain. Required for efficient formation of stress granules. (Microbial infection) Required for internal initiation of translation of human rhinovirus RNA.
Synonyms: D1S155E; UNR
Tractability: Antibody: its Gene Ontology location is reachable by antibodies, with high confidence. PROTAC: UniProt records ubiquitination sites on it; ubiquitination databases record sites on it; its protein half-life has been measured.
Gene: Protein-coding gene on chromosome 1 (114,716,913 to 114,758,704, reverse strand). Ensembl gene ENSG00000009307.
Subcellular location: Cytoplasm; Cytoplasm, Stress granule; Cytoplasm, P-body
Subcellular location (Human Protein Atlas): Cytosol; Endoplasmic reticulum; Golgi apparatus; Plasma membrane
Gene Ontology:
Molecular function: lncRNA binding; protein binding; RISC complex binding; RNA binding; RNA stem-loop binding; mRNA binding; protein-RNA adaptor activity; nucleic acid binding
Biological process: CRD-mediated mRNA stabilization; IRES-dependent viral translational initiation; negative regulation of nuclear-transcribed mRNA catabolic process, deadenylation-dependent decay; nuclear-transcribed mRNA catabolic process, no-go decay; positive regulation of cytoplasmic translation; positive regulation of translation; stress granule assembly; male gonad development; regulation of translational initiation
Cellular component: CRD-mediated mRNA stability complex; cytosol; mCRD-mediated mRNA stability complex; cytoplasm; cytoplasmic stress granule; P-body
Genetic constraint (gnomAD): Loss-of-function variants: 15 observed, 78.29 expected, observed/expected ratio (o/e) 0.19, 90% interval 0.13 to 0.29. The upper end of that interval is the gene's LOEUF score, 0.29, which puts it in group 1 of 6, group 1 being the genes least tolerant of losing a copy. Missense variants: 612 observed, 956.37 expected, observed/expected ratio (o/e) 0.64, 90% interval 0.6 to 0.68. Synonymous variants: 298 observed, 325.66 expected, observed/expected ratio (o/e) 0.92, 90% interval 0.83 to 1.01.
Gene-disease validity (ClinGen):
ClinGen rates the evidence that CSDE1 causes each of these diseases.
complex neurodevelopmental disorder (autosomal dominant): Definitive. A disorder that involves more than one phenotype associated with the central nervous system, including but not limited to intellectual disability, autism, and seizures (epilepsy).
Homologues: Orthologues: chimpanzee CSDE1 (100% identical), dog CSDE1 (99% identical), pig CSDE1 (99% identical), rabbit CSDE1 (99% identical), rat Csde1 (99% identical), mouse Csde1 (98% identical), macaque CSDE1 (98% identical), guinea pig CSDE1 (94% identical), tropical clawed frog csde1 (86% identical), zebrafish csde1 (78% identical), Drosophila melanogaster Unr (47% identical), zebrafish si:dkeyp-121d4.3 (25% identical).
Diseases named in the same sentence as CSDE1 in open-access papers:
CSDE1 is named in the same sentence as 46 diseases in open-access papers, as found by Europe PMC text mining. Sharing a sentence is not in itself a finding about the gene and the disease. The quoted sentences say what the papers report.
melanoma (15 papers, 2017 to 2024). A malignant, usually aggressive tumor composed of atypical, neoplastic melanocytes. "Previous studies have shown that upregulated CSDE1 expression was associated with melanoma through elongation of the oncogene Rac1." (PMID 35490208, 2022). "Comparison showed that 53 of the 274 transcripts we identified as Csde1-associated transcripts were also identified as a Csde1 target in melanoma cells using iCLIP18." (PMID 29422612, 2018). "Furthermore, an elegant recent report showed that CSDE1 promotes immune escape in melanoma by stabilizing the levels of PTPN2 mRNA, which encodes the STAT1 phosphatase TCPTP." (PMID 38600987, 2024). "Increased expression of Csde1 has been associated with melanoma and breast cancer." (PMID 29422612, 2018). "Interestingly, this study also demonstrated that CSDE1 binds to mRNAs encoding regulatory proteins involved in development and neuron projection guidance in melanoma cells." (PMID 29129916, 2017). "In addition, CSDE1 expression was upregulated and associated with the aggressiveness of melanoma." (PMID 35490208, 2022). "Similar to melanoma, CSDE1 maintains the invasive phenotype of colorectal, pancreatic and lung cancer cells, while in squamous cell carcinoma, paraganglioma and pheochromocytoma, CSDE1 behaves as a tumor suppressor." (PMID 38396995, 2024). "Taken together, these results indicate that an increased CSDE1 C/N ratio correlates with malignancy of primary melanoma lesions, and with poor outcome of patients with metastasis." (PMID 38396995, 2024). "An exception is melanoma, where CSDE1 behaves as a versatile ‘Swiss knife’ to promote an invasive phenotype." (PMID 38600987, 2024). "We noticed that CSDE1 can be found in both the cytoplasm and nucleus of melanoma patient samples depending on the sample type." (PMID 38396995, 2024). "Depletion of CSDE1 from melanoma cells dramatically decreased metastasis in mice, whereas CSDE1 over-expression in a non-metastatic cell line markedly increased its metastatic potential." (PMID 38600987, 2024). "In primary melanoma, the CSDE1 C/N ratio increases in samples of nodular histology and with more than two mitoses." (PMID 38396995, 2024). "CSDE1 has been proposed as a predictive marker for anti-PD1 immunotherapy response in melanoma and as a prognostic biomarker helping to guide adjuvant treatment decisions in resectable pancreatic adenocarcinoma." (PMID 38396995, 2024). "Given the extensive involvement of CSDE1 in cancer and its important roles in melanoma progression, we aimed to test its value as a biomarker of prognosis." (PMID 38396995, 2024). "This antibody, which we term G10, specifically detects human CSDE1 via Western blot, as shown by a prominent signal in melanoma cells that disappears after depletion of CSDE1." (PMID 38396995, 2024). "Epigenetic modification (H3K4me3) of the CSDE1 locus by the methyltransferase SMYD3 controls CSDE1 transcription upon mechanical signals in melanoma nascent tumorigenic cells." (PMID 38600987, 2024). "For example, CSDE1 downregulates PTEN mRNA levels in melanoma, while it increases PTEN mRNA translation to prevent squamous cell carcinoma." (PMID 38600987, 2024). "We find that CSDE1 expression is heterogeneous in healthy tissues and, contrary to expectations from an oncoprotein, its levels decrease with melanoma malignancy." (PMID 38396995, 2024). "We then evaluate CSDE1 expression in 149 whole tissue sections including benign nevi, and melanoma primary tumors and metastasis." (PMID 38396995, 2024). "We have previously found that the RBP CSDE1 (also called UNR) behaves as an oncoprotein in melanoma." (PMID 38396995, 2024). "It will be interesting to decipher their potential as melanoma biomarkers and their synergies with CSDE1." (PMID 38396995, 2024).
melanoma (continued). "Consistent with our findings here, previous studies using fibroblasts from human patients, mouse cortical neurons and melanoma cells also showed that depletion of CSDE1 reduced β-catenin expression at the protein level." (PMID 37874038, 2023). "Overexpressed CSDE1 protein has been suggested as a vital component during tumourigenesis including melanoma and glioma." (PMID 36354136, 2022). "It has been found that the regulation of VIM and RAC1 mRNA translation by CSDE1 contributes to melanoma metastasis." (PMID 36354136, 2022). "UNR/CSDE1 influences proliferation under stress conditions, is overexpressed in melanoma tumors and promotes invasion and metastasis partly by inducing translation elongation of targeted mRNAs." (PMID 33662035, 2021). "Studies in a mouse model further suggested that depletion of CSDE1 strikingly reduced the metastasis to the lung, which is a frequent metastatic site for melanoma." (PMID 31987048, 2020). "CSDE1 expression is higher in a variety of melanoma cell lines, including SK-Mel-19, SK-Mel-29, and SK-Mel-103, than in normal melanocytes." (PMID 31987048, 2020). "CSDE1 is an oncogene in melanoma, and suppressing CSDE1 can reduce tumour malignancy in both cancer cells and animal models." (PMID 31987048, 2020). "Depletion of CSDE1 in melanoma cells reduced CSDE1 expression at the protein level, which is consistent with our results." (PMID 31579823, 2019). "These functions of UNR/CSDE1, which involve invasive phenotype, are supported by a previous report in melanoma derived cell lines and tumors." (PMID 31027221, 2019). "The binding of CSDE1 with β-catenin was also reported in a recent study that investigated the CSDE1 targets in melanoma cell." (PMID 31579823, 2019). "It has been previously reported how UNR/CSDE1 regulates direct translation of vimentin in melanoma cells." (PMID 31027221, 2019). "Underlining the importance of CSDE1 in human disease, a comprehensive recent study identified a key role for CSDE1 in melanoma as a regulator of a subset of genes governing cell invasion and metastasis." (PMID 30247708, 2018). "CSDE1 is a known single-stranded RNA binding protein that coordinates post-transcriptional regulation of genes involved in melanoma metastasis." (PMID 30247708, 2018). "Knockdown of Csde1 in these cells reduced expression of Vim via decreased ribosome occupancy in melanoma cells." (PMID 30138317, 2018). "In these cells, CSDE1 induces VIM protein expression with pro-oncogenic effects that contribute to melanoma invasion and metastasis." (PMID 29129916, 2017). "The transcripts of 6 significantly changed proteins (VIM, DNM1, SMARCC2, CSDE1, EIF4A2 and ANXA2) have been previously identified as direct RNA targets of CSDE1 in human melanoma cells." (PMID 29129916, 2017). "In order to obtain a global view of CSDE1 targets, we compared the transcripts bound to endogenous CSDE1 in three large-scale studies performed in melanoma cells, primary mouse keratinocytes (PMK, either under proliferating or senescent conditions), and mouse cardiac endothelial cells (MCEC)." (PMID 38600987, 2024). "In addition to CSDE1, several RBPs have been shown to play roles in melanoma progression, including CELF, CPEB4, IGF2BP1, IGF2BP3, NOVA1 and DDX3X, among others." (PMID 38396995, 2024). "Here, we design a monoclonal antibody useful for IHC in the clinical setting and use it to evaluate the prognosis potential of CSDE1 in an exploratory cohort of 149 whole tissue sections including benign nevi and primary tumors and metastasis from melanoma patients." (PMID 38396995, 2024). "Similarly, to promote melanoma cell aggressiveness CSDE1 downregulates the levels of PTEN mRNA, while it upregulates the levels of PTPN2 and PMEPA1 mRNAs." (PMID 38600987, 2024). "The G10 antibody was then used to assess CSDE1 levels in nevi and melanoma samples." (PMID 38396995, 2024).
melanoma (continued). "In addition, CSDE1 mediates immune evasion of melanoma cells by modulating the levels of the phosphatase TCPTP and thereby decreasing STAT1 phosphorylation." (PMID 38396995, 2024). "Furthermore, in melanoma cells CSDE1 interacts with AGO2 in the miRISC complex and counteracts the silencing of PMEPA1 mRNA by miR-129-5p." (PMID 38600987, 2024). "Besides, CSDE1 was also verified to have tumor-promoting effects in melanoma by regulating the translation of vimentin and Rac-1." (PMID 35923244, 2022). "Additionally, depletion of CSDE1 decreased melanoma tumour growth and metastatic capacity, and overexpression of CSDE1 promoted migration and invasion." (PMID 31987048, 2020). "UNR/CSDE1 has been studied in breast, melanoma, pancreatic and prostate cancer." (PMID 31027221, 2019). "Recent studies identified Csde1 targets in melanoma cells and Drosophila melanogaster." (PMID 29422612, 2018). "Nop56 and Ebna1bp2 also interacted with Csde1 in melanoma cells." (PMID 29422612, 2018). "Thus, consistent with the reported dependency of SELF melanoma associated antigen expression upon AIRE51, 52, GAPDH, TYRP2 and CSDE1, three well-characterized SELF proteins, are regulated by AIRE in B16-OVA cells, but expression of stably transfected, CMV-driven OVA protein was independent of AIRE." (PMID 39606441, 2024). "However, an iCLIP approach demonstrated that Csde1 binds the 3’UTR of Vim in human melanoma cells." (PMID 30138317, 2018). "We further correlated CSDE1 levels in primary tumors with melanoma indicators of malignancy, such as Breslow depth and pathological classification (superficial spreading or nodular, NCCN melanoma guidelines V2.2020)." (PMID 38396995, 2024). "We have previously found that the RNA-binding protein Cold Shock Domain containing protein E1 (CSDE1) promotes invasion and metastasis of melanoma, the deadliest form of skin cancer and also a highly heterogeneous disease in need of predictive biomarkers and druggable targets." (PMID 38396995, 2024). "In melanoma, CSDE1 promotes translation elongation of VIM without altering its steady-state transcript levels." (PMID 29129916, 2017).
autism (6 papers, 2018 to 2026). Persistent deficits in social interaction and communication and interaction as well as a markedly restricted repertoire of activity and interest as well as repetitive patterns of behavior. "Among disease-associated genes were those associated with autism (CSDE1) and Parkinson’s disease (LHFPL2)." (PMID 37106565, 2023). "Attesting to its important roles in post-transcriptional regulation, Unr/CSDE1 has been linked to diseases, including Diamond-Blackfan anemia, autism, and cancer progression." (PMID 32697992, 2020). "Whole exome sequencing of 918 individuals found that a de novo loss of function mutation in CSDE1 was strongly associated with autism." (PMID 31987048, 2020). "Here, we report a significant burden of heterozygous, likely gene-disrupting variants in CSDE1 (encoding a highly constrained RNA binding protein) among patients with autism and related neurodevelopmental disabilities." (PMID 31579823, 2019). "We report a significant association of both de novo and inherited truncating variants in CSDE1 among pediatric patients with autism and more broadly defined NDDs." (PMID 31579823, 2019). "In addition, another genome-wide association study on autism that used two Chinese cohorts for discovery (n = 2150) and three data sets of European ancestry populations for validation suggested that CSDE1 was a candidate gene for autism (P = 5.51 × 10− 6)." (PMID 31987048, 2020).
pheochromocytoma (6 papers, 2018 to 2024). "CSDE1 loss-of-function mutations and deletions define a Wnt-altered subtype of pheochromocytomas and paragangliomas." (PMID 35975235, 2022). "Cluster 3 PPGLs contain pheochromocytomas that are overrepresented in somatic UBTF-MAML3 fusion genes and CSDE1 mutations." (PMID 35205664, 2022). "Our analysis also shows frequent deletions of CSDE1 in the TCGA PCPG (pheochromocytoma and paraganglioma) cohort." (PMID 35975235, 2022). "Additionally, activating mutations of Wnt-signalling pathway or its components, including somatic mutations of CSDE1 (cold shock domain containing E1) and MAML3 (mastermind like transcriptional coactivator 3) genes are known as cluster 3 in phaeochromocytomas and paragangliomas." (PMID 33114456, 2020).
breast carcinoma (5 papers, 2013 to 2024). "In the Chinese breast cancer set, CSDE1 was determined to be one of the principal component genes that predicted high-risk groups using comparative genome hybridization and gene expression microarray." (PMID 35490208, 2022). "In breast cancer cells, CSDE1 mRNA is targeted by miR-525-5p." (PMID 38600987, 2024). "In addition, for breast cancer, which is the most common cancer affecting women, CSDE1 mRNA expression was nearly 10-fold higher in MCF-7 breast cancer cells than in normal cell lines." (PMID 31987048, 2020). "The lncRNA BC200 is involved in preserving this cytoplasmic distribution in breast cancer MCF-7 cells, as depletion of BC200 leads to accumulation of CSDE1 in intranuclear foci and reduced CSDE1 levels." (PMID 38600987, 2024). "However, although most reported functions of CSDE1 are cytoplasmic, it has been recently proposed that CSDE1 interacts with RNApol-II and CDK7 to promote transcription in breast cancer cells." (PMID 38396995, 2024). "In addition, CSDE1 expression was upregulated in TNBC cell lines compared to that in non-TNBC cell lines and the non-cancerous breast cancer MCF10A cells." (PMID 35490208, 2022).
glioma (4 papers, 2020 to 2024). A benign or malignant brain and spinal cord tumor that arises from glial cells (astrocytes, oligodendrocytes, ependymal cells). "High expression of CSDE1 was associated with poor prognosis in glioma and pancreatic ductal adenocarcinoma (PDAC)." (PMID 31987048, 2020). "Although these findings support a beneficial role of CSDE1 in glioma, a conflicting report suggests that CSDE1 promotes glioma cell migration and is significantly upregulated in patient samples compared to normal brain tissues." (PMID 38600987, 2024). "CSDE1 expression was also significantly higher in glioma cells and tissues than it was in normal human astrocytes and brain tissues." (PMID 31987048, 2020). "In addition, tumor suppressor roles of CSDE1 can be inferred from studies in glioma, where CSDE1 was identified as the target of the drug clofoctol." (PMID 38600987, 2024). "In addition, higher CSDE1 expression was correlated with poorer survival in glioma patients (P = 0.0177)." (PMID 31987048, 2020). "The CSDE1 mRNA expression level was also higher in grade IV glioma than it was in grade II and III patients (P < 0.001) according to the data released by the Chinese Glioma Genome Atlas (CGGA)." (PMID 31987048, 2020).
lung carcinoma (4 papers, 2020 to 2025). "This study investigates the role of CSDE1 in lung cancer progression and its impact on the tumor immune microenvironment." (PMID 41353256, 2025). "Recently, long intergenic non-protein coding RNA 205 (Linc00205) have been found to promote malignancy in lung cancer by recruiting the RNA-binding protein FUS to stabilize CSDE1 mRNA, which enhances lung cancer cell proliferation, apoptosis, and migration." (PMID 35179516, 2022). "We found that CSDE1 promotes lung cancer progression in vivo but not in vitro." (PMID 41353256, 2025).
colorectal cancer (3 papers, 2019 to 2022). A primary or metastatic malignant neoplasm that affects the colon or rectum. "Then, the aim of this study is to evaluate the role of CSDE1/UNR in colorectal cancer progression and maintenance of aggressive phenotype." (PMID 31027221, 2019). "The purpose of this study is to evaluate, for the first time, the role of UNR/CSDE1 in colorectal cancer carcinogenesis." (PMID 31027221, 2019). "Although the sample size to achieved this conclusion was small, an in silico analysis using The Cancer Genome Atlas (TCGA)-Colorectal Cancer Dataset showed similar results: patients with high CSDE1 expression presented shorter mean progression-free survival than patients with low CSDE1 expression." (PMID 31440515, 2019). "Another investigation discovered that CSDE1 could regulate the expression of c-Myc, Rac-1, PTEN, and vimentin in colorectal cancer." (PMID 35923244, 2022).
Diamond Blackfan Anemia (3 papers, 2018). A congenital aregenerative and often macrocytic anemia with erythroblastopenia. "Nevertheless, Csde1 is strongly upregulated in erythroblasts and we previously reported reduced Csde1 expression in Diamond Blackfan Anemia." (PMID 29634759, 2018). "Csde1 expression is impaired in the severe congenital anemia Diamond Blackfan Anemia (DBA), and reduced expression of Csde1 in healthy erythroblasts impaired their proliferation and differentiation." (PMID 29422612, 2018).
metastatic disease (3 papers, 2019 to 2023). "Interestingly, CSDE1 expression associated significantly to metastatic disease in CRC (p = 0.039)." (PMID 31027221, 2019).